SOST (sclerostin)
Diseases named in the same sentence as SOST in open-access papers (continued):
Sharing a sentence is not in itself a finding about the gene and the disease.
atherosclerosis (continued). "In male patients with atherosclerosis, the levels of serum sclerostin are positively correlated with aging, but this difference has not found in women." (PMID 34901023, 2021). "Higher sclerostin levels were indicators of more progressive atherosclerosis development that leads to increased incidence of cardiovascular events." (PMID 33800939, 2021). "A previous study revealed that the incidence of artery atherosclerosis and all-cause mortality in MHD patients was correlated with increased sclerostin." (PMID 34976409, 2021). "In healthy animals and in mouse models of atherosclerosis, effects of sclerostin neutralization on cardiovascular function, vascular calcification, and transcription were nonsignificant." (PMID 33776907, 2021). "In the apolipoprotein E-deficient (ApoE61/61) mouse model, the administration of recombinant mouse sclerostin protein, an inhibitor of the Wnt signaling pathway, inhibited angiotensin II-induced atherosclerosis." (PMID 32138681, 2020). "They reported that SOST inhibits angiotensin II (AngII)-induced AA in both the thoracic and abdominal aorta of the mouse model, and also inhibits AngII-induced atherosclerosis." (PMID 32640551, 2020). "Clinical studies have reported a correlation between serum sclerostin levels and atherosclerosis in obese and diabetic patients." (PMID 32458213, 2020). "Further studies are needed to determine the precise contributions of sclerostin and the Wnt-β-catenin axis to atherosclerosis." (PMID 32458213, 2020). "Recently, sclerostin, a bone-derived protein, has been shown to play a key role in atherosclerosis progression." (PMID 31677125, 2020). "In ApoE−/- mice treated with angiotensin II, sclerostin overexpression induced inhibitory effects on the progression of aortic aneurysm and atherosclerosis." (PMID 32544571, 2020). "The role of sclerostin in inflammation, AA, and atherosclerosis deserves further study." (PMID 40429697, 2025). "Furthermore, it has been reported that the transgenic introduction of sclerostin in ApoE−/− (SOSTTg.ApoE−/−) mice and the administration of recombinant sclerostin inhibited AngII-induced AA and atherosclerosis development." (PMID 40429697, 2025). "Nevertheless, whether inhibition of endogenous levels of sclerostin could influence the inflammation and the progression of AA and atherosclerosis remains unknown." (PMID 40429697, 2025). "In patients with CAD, higher sclerostin levels have been correlated with less severe vascular calcification and improved vascular health, indicating a potential protective role against the progression of atherosclerosis." (PMID 39767786, 2024). "Sclerostin has been found in atherosclerotic plaques and may be involved in the development of atherosclerosis and vascular calcification." (PMID 38714960, 2024). "Additionally, in older patients undergoing percutaneous coronary intervention, elevated sclerostin levels were associated with improved survival rates and fewer adverse cardiovascular events, which may be attributed to its role in mitigating the progression of atherosclerosis." (PMID 39767786, 2024). "Genetic liability to atherosclerosis‐related diseases or risk factors showed little evidence of a reverse effect on sclerostin." (PMID 37096546, 2023). "Sclerostin could play a protective role in the development of atherosclerosis in T2D patients by reducing calcium deposits, decreasing proliferation and inflammation, and promoting cell survival in VSMCs under calcifying conditions." (PMID 37919715, 2023). "In contrast, little evidence for a causal effect of lower sclerostin on any other atherosclerosis‐related disease or risk factor was identified." (PMID 37096546, 2023). "We considered the SOST cis variant and B4GALNT3, SERPINA1, and RIN3 trans variants identified above as possible instruments for MR analyses of the effect of lower sclerostin levels on atherosclerosis risk." (PMID 37096546, 2023).
atherosclerosis (continued). "Transgenic introduction of human sclerostin in ApoE-/- mice could suppress AA and atherosclerosis progression." (PMID 35966595, 2022). "Therefore, it is suggested that sclerostin is not only involved in the regulation of bone formation but also in the pathophysiological process of atherosclerosis." (PMID 35216490, 2022). "As VSMCs were considered as major precursors contributing to osteochondrogenesis and calcification in atherosclerosis, it was speculated that serum sclerostin may play an endocrine modulatory role in atherosclerosis development." (PMID 35546224, 2022). "Since Wnt signaling pathways exerted a multifunctional role in endothelial dysfunction, the proliferation and migration of vascular smooth muscle cells (VSMCs), inflammation processes and vascular calcification progression, sclerostin was inevitably involved in the development of atherosclerosis." (PMID 35546224, 2022). "In addition, the positive correlation between sclerostin and VC, sclerostin and atherosclerosis, and sclerostin and arterial stiffness in patients with T2DM was well-proved by cross-sectional studies." (PMID 35966090, 2022). "Another observational study was also performed to assess the relation of serum sclerostin with atherosclerosis severity by SYNTAX score in patients with stable coronary artery disease or ACS, but the results failed to support direct relationship between sclerostin and CAD severity." (PMID 35546224, 2022). "As the real contribution of sclerostin to the development of atherosclerosis is still uncertain, further mechanistic and clinical studies are needed to confirm our speculation." (PMID 35546224, 2022). "It was reported that transgenic introduction of human sclerostin could inhibit inflammatory cytokines and chemokines, while prevent AA and atherosclerosis progression in ApoE-/- mice with angiotensin II (AngII) infusion." (PMID 35966595, 2022). "The parameters indicating AA and atherosclerosis progression were detected in Col1a2+/G610C.ApoE-/- mice with AngII infusion, after administration of humanized therapeutic sclerostin antibody (Hongmed-Infagen/Creative Biolabs, 25 mg/kg, twice per week) for four weeks." (PMID 35966595, 2022). "In consequence, sclerostin is suspected to play a part in atherosclerosis development." (PMID 33800939, 2021). "ApoE-/- mice stimulated with angiotensin II develop aortic aneurysms and atherosclerotic plaques, but when these mice also overexpressed human sclerostin or were injected with recombinant mouse sclerostin they were protected from aortic aneurysms and atherosclerosis." (PMID 33776907, 2021). "Based on this evidence, we hypothesized that sclerostin plays an important role in the pathophysiology of atherosclerosis." (PMID 32458213, 2020). "In early atherosclerosis in obesity, the Wnt/β-catenin signaling pathway inhibitor sclerostin could serve as a useful biomarker." (PMID 32138681, 2020). "DKK-1 and sclerostin, two Wnt pathway inhibitors, are also involved in the atherosclerosis process." (PMID 28553649, 2017). "Additionally, SOST can inhibit the Ang II-induced formation of atherosclerosis and aneurysms, suggesting that SOST modulation may serve as a potential strategy for inhibiting these conditions." (PMID 40563496, 2025). "Conversely, aortic sclerostin expression was shown to be downregulated in a murine model of abdominal aortic aneurysm, while transgenic overexpression or exogenous administration of sclerostin was demonstrated to mitigate the development of abdominal aortic aneurysm and atherosclerosis." (PMID 40307216, 2025). "Furthermore, it was reported that transgenic introduction of human sclerostin could inhibit inflammatory cytokines and chemokines, while prevent AA and atherosclerosis progression in ApoE-/- mice with AngII infusion." (PMID 35966595, 2022). "Sclerostin might play a role in atherosclerosis development." (PMID 33800939, 2021). "Therefore, upregulation of SOST inhibits AA and atherosclerosis development." (PMID 32640551, 2020).
atherosclerosis (continued). "Background and Objectives: Sclerostin and dickkopf-1 (DKK1), which are Wnt inhibitors, are involved in vascular calcification and atherosclerosis." (PMID 40731833, 2025). "Such an effect is likely mediated by sclerostin's well‐recognized action as a WNT inhibitor, given the contribution of WNT signalling to the development of atherosclerosis." (PMID 37096546, 2023). "Bone-related proteins (such as sclerostin and osteoprotegerin [OPG]) are involved in the development of atherosclerosis." (PMID 35546224, 2022). "In conclusion, the results presented here indicate that sclerostin level increases with the deterioration of renal function in patients with CKD 3–5ND, and that sclerostin plays a critical role in the development of atherosclerosis." (PMID 32458213, 2020). "Thus, sclerostin may play an important role in the process of atherosclerosis." (PMID 32458213, 2020). "The studies of atherosclerosis and aortic aneurysm in SOSTki.ApoE-/- mice and sost-/-.ApoE-/- mice collectively indicated the cardiovascular protective action of sclerostin." (PMID 41276911, 2025). "In a previous study involving non-CKD patients, it was found that serum Sclerostin levels were significantly elevated in patients with atherosclerosis, vascular calcification, and valvular calcification." (PMID 38714960, 2024). "In the ApoE −/−model of atherosclerosis, inhibiting the sclerostin loop 3 did not increase vascular calcification, but did increase bone remodeling." (PMID 36776982, 2023). "This study aims to investigate the potential protective role of sclerostin in the development of atherosclerosis in humans, which has not been previously explored." (PMID 37919715, 2023). "Unfortunately, not many research papers have analyzed the pathophysiologic relationships between atherosclerosis and sclerostin in subjects without advanced CKD." (PMID 33800939, 2021). "Few studies have examined the correlation between serum sclerostin level and atherosclerosis in non-dialysis patients with CKD (CKD-ND)." (PMID 32458213, 2020). "Here we investigated the relationship between sclerostin and atherosclerosis in non-dialysis patients with stage 3–5 CKD (CKD 3–5ND)." (PMID 32458213, 2020). "Taken together, the aggravative effect of sclerostin inhibition on inflammation and atherosclerosis could not be excluded." (PMID 40429697, 2025). "Moreover, serum SOST levels are positively correlated with aging in male patients with atherosclerosis, a correlation absent in females." (PMID 40563496, 2025). "Another report indicated that the blood sclerostin level could serve as a useful biomarker of early atherosclerosis in obese individuals without a previous history of cardiometabolic disorders." (PMID 35216490, 2022). "Furthermore, Apc001PE showed no influence on the suppressive effect of sclerostin on inflammatory cytokines and chemokines expression, AA and atherosclerosis progression in hSOSTki.Col1a2+/G610C.ApoE-/- mice with AngII infusion." (PMID 35966595, 2022). "Considering the involvement of the canonical Wnt signaling in the development and progression of atherosclerosis, a possible role for sclerostin could be reserved." (PMID 32366042, 2020). "Sclerostin level was non-normally distributed and was log transformed, and multiple stepwise regression analysis was carried out with sex, age, body mass index (BMI), eGFR, iPTH, 25(OH) vitamin D, serum calcium, phosphorus, DM, and atherosclerosis as covariates." (PMID 32458213, 2020). "In conclusion, to the best of our knowledge, this study is the first to investigate the levels of SOST in Egyptian female patients with T2DM with and without atherosclerosis and the potential relation between SOST and irisin in the 2 studied T2DM cohorts." (PMID 30403705, 2018).
atherosclerosis (continued). "Serum sclerostin levels were significantly higher in hemodialysis patients with carotid artery atherosclerosis (p = 0.016) and T2DM patients with atherosclerosis (p = 0.006), compared to their counterparts without atherosclerosis." (PMID 40429697, 2025). "We speculate that the elevated sclerostin may partly originate from atherosclerotic plaques in CKD patients, which suppresses atherosclerosis in a negative feedback mechanism by inhibiting Wnt signaling, thereby protecting against plaque development." (PMID 32458213, 2020).
breast carcinoma (34 papers, 2011 to 2025). "High levels of DKK-1 are associated with osteolytic damage in multiple myeloma and breast cancer, whereas a reduction in sclerostin is linked to osteoblastic repair in prostate cancer." (PMID 40426987, 2025). "High sclerostin expression has been shown to be associated with breast cancer bone metastasis; perhaps most interestingly in light of findings presented within this study, sclerostin has been shown to interact with STAT3 to enhance TGF-β/K-Ras signalling." (PMID 40192943, 2025). "High levels of SOST expression were detected in 24.2% (102/422) of the breast cancer tissues and significantly associated with worse overall and disease-free survival (P < 0.001)." (PMID 36581888, 2022). "SOST expression in 442 breast cancer tissues was characterized by immunohistochemistry and statistically analyzed for the association with breast cancer bone metastases." (PMID 36581888, 2022). "In this study, we found that up-regulated SOST expression in breast cancer tissues was significantly associated with the development of breast cancer bone metastasis in a population of 422 breast cancer patients." (PMID 36581888, 2022). "In this study, we found that up-regulated SOST expression was associated with worse prognosis in breast cancer patients." (PMID 36581888, 2022). "We found that up-regulated SOST expression was associated with breast cancer bone metastases and worse survival of breast cancer patients." (PMID 36581888, 2022). "In addition, anti-sclerostin antibody treatment prevented breast cancer-induced bone loss by enhancing osteoblast function and simultaneously inhibiting bone resorption." (PMID 32092997, 2020). "Sclerostin encoded by SOST is produced primarily by osteocyte, and may be implicated in promoting tumor growth, bone metastasis and osteolysis in breast cancer." (PMID 32188434, 2020). "In breast cancer, the SOST gene was found to interact with signal transducer and activator of transcription 3 (STAT3) and enhance TGF-β/KRAS (Kirsten rat sarcoma virus) signaling, leading to increased tumor growth and bone metastasis." (PMID 38247829, 2024). "Mendoza-Villanueva and colleagues have shown that Runx2 and CBFb inhibit osteoblast differentiation in bone metastatic breast cancer cells and that this inhibition is mediated by the induction of sclerostin expression." (PMID 38247829, 2024). "In vivo models in mice with breast cancer-related bone metastases have shown that pharmacological sclerostin inhibition reduces metastatic burden, prolongs animal survival and prevents cancer-related bone destruction." (PMID 38247829, 2024). "In some studies, researchers have identified a correlation between elevated expression of Sclerostin (SOST) and the occurrence of bone metastasis in breast cancer, as well as a poorer prognosis for breast cancer patients." (PMID 38041134, 2023). "Intriguingly, a recent study in a mouse model of breast cancer bone metastasis, which can lead to a mix of lytic and blastic lesions, showed that sclerostin production by cortical osteocytes is suppressed only in areas adjacent to tumor cells." (PMID 37174109, 2023). "Intriguingly, the authors of this manuscript reported that pre-treatment with anti-sclerostin increased tumor area only when MDA-MB-231 breast cancer cells were used." (PMID 37174109, 2023). "Recently, a study explored the role of sclerostin in bone formation and its potential impact on the spread of breast cancer to the bone." (PMID 38260135, 2023). "In breast cancer bone metastasis, treatment with anti-sclerostin in a mouse model with established bone metastasis after cardiac inoculation reduced the growth of MDA-MB-231 breast cancer cells." (PMID 37174109, 2023). "This suggests that blocking sclerostin amplifies canonical Wnt signaling in breast cancer cells that are responsive to Wnt ligands, consequently promoting increased bone metastasis." (PMID 38260135, 2023).